NUAK1 (NUAK family kinase 1)
Diseases named in the same sentence as NUAK1 in open-access papers (continued):
Sharing a sentence is not in itself a finding about the gene and the disease.
ovarian carcinoma (continued). "Subsequently, the remaining prognostic biomarkers from other cancer types were also assessed by OSov, which demonstrated that these genes (SFRP4, NUAK1, MFAP2, PLIN1 and EFNB2) exhibited good performance in predicting ovarian cancer patient outcome." (PMID 35053021, 2021). "Although there is no direct evidence of clinical association with progression of disease in serous ovarian cancer, there are in vitro studies that implicate NUAK1 (ARK5) with invasion and progression in ovarian cancer cell lines." (PMID 27756408, 2016). "Elevated NUAK1 transcript expression and shorter PFS was validated by quantitative PCR analyses in ovarian cancer tissue from HGSOC patients with short vs. long disease progression." (PMID 27833898, 2016). "Further, we provide functional evidence that NUAK1 regulates tumor cell migration in both chemosensitive (OV90) and chemoresistant (E3) ovarian cancer cell lines." (PMID 27833898, 2016). "NUAK1 downregulation with siRNA in OV90 ovarian cancer cells revealed that NUAK1 downregulation does not affect the chemoresistance of these cells to cisplatin or paclitaxel." (PMID 34685740, 2021). "ARK5/NUAK1 and HOXA10, as the regulatory factors in EMT cascade loop, were remarkably upregulated, when compared with adjacent normal tissues, thus enhancing invasiveness of ovarian cancer." (PMID 33493131, 2021). "Logistic regression modeling demonstrated a relationship between elevated NUAK1 expression and aggressive clinic-pathologic features, as well as select molecular subtypes in ovarian cancer patients, but not with BRCA1/2 status [odds ratio (OR) = 0.93, p > 0.05]." (PMID 27833898, 2016).
hepatocellular carcinoma (11 papers, 2015 to 2025). A malignant tumor that arises from hepatocytes. "Western blotting, immunofluorescence, real time PCR, and immunohistochemical staining were used to investigate the underlying mechanisms by which NUAK1 regulates PD-L1 expression in hepatocellular carcinoma." (PMID 39901136, 2025). "NUAK1 is associated with metastasis and drug resistance in hepatocellular carcinoma (HCC)." (PMID 39901136, 2025). "Subsequently, we overexpressed β-catenin and examined its effect on PD-L1 expression in NUAK1-knockdown hepatocellular carcinoma cell lines." (PMID 39901136, 2025). "Elevated NUAK1 expression has been observed in hepatocellular carcinoma, gastric cancer, ovarian cancer, glioma and other tumors." (PMID 39901136, 2025). "This study revealed a novel role for NUAK1, which promotes the transcriptional expression of PD-L1 by activating GSK3β/β-catenin signaling pathway, leading to immune escape of hepatocellular carcinoma." (PMID 39901136, 2025). "To assess the role of NUAK1 in immune escape in hepatocellular carcinoma, we initiated our study by analyzing the mRNA expression of NUAK1 in HCC and its prognostic significance using the Gene Expression Omnibus (GEO) database." (PMID 39901136, 2025). "NUAK1-downregulation increases E-cadherin expression and decreases vimentin in hepatocellular carcinoma (HCC) cells and gastric cancer (GC) tissue." (PMID 34685740, 2021). "NUAK1 depletion released pro-apoptotic signals both in vitro and in vivo in hepatocellular carcinoma, establishing NUAK1 as a survival factor for tumor cells." (PMID 30622137, 2019). "Accordingly, NUAK1 suppresses apoptosis induced by nutrient starvation and death receptors in hepatoma cells." (PMID 30622137, 2019).
melanoma (11 papers, 2014 to 2024). A malignant, usually aggressive tumor composed of atypical, neoplastic melanocytes. "The most significant region associated with melanoma occurrence was located on chromosome 5 harboring the NUAK1 gene encoding AMP-activated protein kinase (AMPK)-related protein kinase 5 (ARK5)." (PMID 31717496, 2019). "One of these regions, that extended over 3 Mb, was associated with both melanoma occurrence and ulceration and several lines of evidence make NUAK1 the best candidate gene in that region." (PMID 29963229, 2018). "NUAK1 levels are deregulated in various cancer tissues and cell lines, including brain cancer, melanoma, and different types of reproductive tissue-derived cancer cells, such as breast, ovarian, cervix, and prostate." (PMID 34685740, 2021). "Among the seven suggestive regions for ulceration, an interesting one was located on SSC5, nearby NUAK1 as for melanoma occurrence." (PMID 29963229, 2018). "It has been well documented that miR-211 is a lineage-specific miRNA which is highly expressed in the melanocytic lineage and has been associated with melanoma cell invasiveness via its direct regulation of POU3F2 (BRN2), IGF2R, TGFBR2, NFAT5, and NUAK1." (PMID 25980496, 2015). "Inhibition of miR-211 also increases NUAK1 expression and decreases melanoma adhesion." (PMID 31652435, 2019). "NUAK1 is an AMPK-related kinase that favors melanoma invasion in vitro." (PMID 29963229, 2018). "Thus further experiments are needed to understand how NUAK1 could affect melanoma growth in pigs." (PMID 29963229, 2018). "Indeed, analysis of the cancer genome atlas (TCGA) database revealed NUAK1 and NUAK2 deregulation in lung, breast, liver, ovarian, and melanoma tumors." (PMID 34685740, 2021).
nasopharyngeal carcinoma (11 papers, 2019 to 2023). A carcinoma arising from the nasopharyngeal epithelium. "For instance, the pathogenic role of miR-145a-5p in nasopharyngeal carcinoma is mediated by its inhibition of NUAK Family SNF1-like Kinase 1 (NUAK1) expression." (PMID 36763283, 2023). "LINC00958 acts as a ceRNA to regulate the miR-625/NUAK1 axis, and affects the invasion and metastasis of nasopharyngeal carcinoma cells." (PMID 37576402, 2023). "For example, LINC00958 sponges miR-625 and suppresses miR-625-mediated NUAK1 inhibition in nasopharyngeal carcinoma and miR-625-mediated LRRC8E inhibition in cervical cancer." (PMID 35223488, 2022). "LINC00958 facilitates cell growth by reducing miRNA-625 and promoting NUAK family SnF1-like kinase-1 (NUAK1) in nasopharyngeal carcinoma." (PMID 34672237, 2021). "SNHG1 can also activate the expression of NUAK1 by downregulating miR-145-5p and thus induce epithelial-mesenchymal transition in nasopharyngeal carcinoma cells." (PMID 32497022, 2020). "LncRNA SNHG1 promoted the expression of NUAK1 by down‐regulating miR‐145‐5p and thus promoted the aggressiveness of nasopharyngeal carcinoma cells through AKT signalling pathway and induced epithelial‐mesenchymal transition (EMT)." (PMID 29575772, 2019). "Transfection was conducted to construct nasopharyngeal carcinoma cells with different expressions of SNHG1, miR‐145‐5p and NUAK1." (PMID 29575772, 2019).
pancreatic cancer (11 papers, 2015 to 2025). "Elevated NUAK1 expression is also associated with poor pancreatic ductal adenocarcinoma survival as inactivating NUAK1 reduces pancreatic cancer proliferation." (PMID 39735555, 2025). "Loss of NUAK1 has recently been showed to trigger genomic instability and suppress tumor cell growth in pancreatic cancer." (PMID 37919754, 2023). "Here, we reveal a requirement for NUAK1 to sustain proliferation of pancreatic cancer cells in vitro and identify a conserved role for NUAK1 in governing centrosome replication through GSK3β‐dependent control of PLK4 protein levels." (PMID 36975767, 2023). "In a recent parallel study, KI-301670, a new NUAK1 inhibitor, showed an anti-tumor effect by directly suppressing pancreatic cancer cell growth." (PMID 38135881, 2023). "NUAK1 overexpression in a pancreatic cancer mouse model increased metastasis." (PMID 32429240, 2020). "In pancreatic cancer, NUAK1 is specifically up-regulated and the down-regulation by miR-96 is capable of impeding the proliferation, migration and invasion of MIA PaCa-2 pancreatic cancer cells." (PMID 33750398, 2021). "TSmiR, miR-96 has been reported to inhibit pancreatic cancer cell proliferation, migration and invasion by 3′-UTR of Novel (nua) kinase family 1 (NUAK1), an oncogene in pancreatic cancer." (PMID 27240340, 2016). "Previous studies have shown that NUAK1 activates MT1-MMP, which results in promoting the metastasis of breast and pancreatic cancer via activation of MMP-2 and MMP-9, so miR-203-driven invasion of HNSCC cells may be regulated by a pathway that is distinct from EMT induction." (PMID 26882562, 2016).
multiple myeloma (10 papers, 2015 to 2024). "NUAK1 was additionally shown to regulate mitochondrial dynamics, with elevated fusion observed in NUAK1-deleted Myeloma cells and more fragmented mitochondria evident in NUAK1-proficient cells." (PMID 38939918, 2024). "In this study, we found SEs driving known oncogenes (ST3GAL6 and ADM) as w critical subtype-specific drivers (MAF and NUAK1) in myeloma pathogenesis." (PMID 33579893, 2021). "Elevated expression of NUAK1 in Multiple Myeloma was shown to be induced by members of the large MAF transcription factor family, which are homologous to the avian retroviral oncogene v-Maf, and two functional MAF response elements were identified in the NUAK1 promoter region." (PMID 38939918, 2024).
glioma (7 papers, 2015 to 2025). A benign or malignant brain and spinal cord tumor that arises from glial cells (astrocytes, oligodendrocytes, ependymal cells). "Although we centered our analysis on NUAK2, NUAK1—its closely related kinase—has also been implicated in glioma progression, suggesting that both kinases may play complementary or distinct roles in disease pathogenesis." (PMID 40770117, 2025). "Indeed, statistical analysis for survival rate in glioma showed that NUAK1 upregulation is associated with poor survival, although it was not statistically significant (p = 0.051)." (PMID 34685740, 2021). "Intriguingly, curated data from glioma male patient samples exhibited a survival rate similar to those samples with low NUAK1 expression." (PMID 34685740, 2021). "On the contrary, curated data from glioma female patient samples revealed a significant correlation between NUAK1 overexpression and poor survival." (PMID 34685740, 2021). "Additionally, NUAK1 mRNA levels were significantly lower in both low- and high-grade gliomas than in normal brain tissues (Fig. EV3E)." (PMID 40770117, 2025). "Next, we examined the expression of NUAK1 in the four glioma cell lines used in these studies." (PMID 40770117, 2025). "Additionally, NUAK1 has been also shown to be upregulated in glioma patient samples." (PMID 34685740, 2021). "To examine their relationship more closely, we assessed their expression patterns across development and found that NUAK1 did not share the same dynamic expression pattern across development as NUAK2, nor did its expression correlate with glioma tumor grade or patient survival." (PMID 40770117, 2025).
Alzheimer disease (6 papers, 2016 to 2024). A progressive, neurodegenerative disease characterized by loss of function and death of nerve cells in several areas of the brain leading to loss of cognitive function such as memory and language. "MiR-211-5p was able to inhibit cortical neuron differentiation and survival via NUAK1 repression, which might contribute to the synaptic failure, neuronal loss and cognitive dysfunction in Alzheimer’s disease (AD)." (PMID 34151707, 2021). "A final target of NUAK1 worth mentioning for its clinical relevance in Alzheimer’s disease is TAU (encoded by MAPT), independently found by two separate groups to be stabilised upon phosphorylation of S356 by NUAK1." (PMID 38939918, 2024). "NUAK1 was found in TAU aggregates in Alzheimer’s disease post-mortem brain tissue, while genetic reduction or pharmacologic inhibition of NUAK1 reduced TAU phosphorylation, stability and accumulation in murine brains." (PMID 38939918, 2024). "A recent study showed that NUAK1 mediates the phosphorylation of the microtubule associated protein TAU on S356 and might be involved in tauopathies such as Alzheimer’s disease." (PMID 30327473, 2018). "We explore the impact of WZ4003 in both wildtype and APP/PS1 cultures, to assess whether NUAK1 inhibition has differential impacts on models of Aβ pathology, partially replicating changes seen in Alzheimer’s disease, where dysregulated Aβ processing is thought to drive downstream changes to tau." (PMID 38175261, 2024).
colon cancer (6 papers, 2020 to 2023). "Moreover, NUAK1 loss reduces tumour-initiating capacity in colon cancer spheroids." (PMID 32429240, 2020). "NUAK1 has been proposed as a key facilitator of the adaptive antioxidant response in colon cancer, playing a protective role against high oxidative stress." (PMID 32754444, 2020).
gastric cancer (6 papers, 2020 to 2025). A primary or metastatic malignant neoplasm involving the stomach. "Our findings were in agreement with a previous report, which showed that knockdown of NUAK1 expression remarkably suppresses gastric cancer cell invasion and metastasis via regulating EMT, rather than proliferation in vitro and in vivo." (PMID 37919754, 2023). "Consistent with our findings in this study, a previous report has showed that knocking down NUAK1 remarkably suppressed invasion and metastasis, as well as down-regulation of the mTOR/p70S6k signals, Slug and SIP1 in gastric cancer." (PMID 37919754, 2023). "Also, NUAK1 can provide the tumor cell with resistance to chemotherapy by upregulating the STAT/GLI1/SOX2 signaling pathway, as indicated by a recent study on gastric cancer." (PMID 41441397, 2025).
prostate carcinoma (6 papers, 2017 to 2024). A carcinoma that arises from epithelial cells of the prostate gland. "In addition, the mRNA of NUAK1 was similarly highly expressed in the prostate cancer cell lines (sequentially PC3, DU145, and LNCaP)." (PMID 39391236, 2024). "Additionally, while CDC20, COL1A2 and S100A10 possess recognized pro-oncogenic activities, the precise roles of B4GALNT4 and NUAK1 in prostate cancer warrant elucidation." (PMID 39391236, 2024). "The tumor suppressor features of miRNA-642 was also confirmed by an alteration of expression of potential target genes, such as WT1, NUAK1, RASSF3, SKP2, GPS2 and IGFBP3, in prostate cancer." (PMID 37108073, 2023).
liver fibrosis (5 papers, 2022 to 2025). "This positive feedback pathway exacerbates liver fibrosis and blocking NUAK1 expression significantly improves liver fibrosis." (PMID 37576865, 2023).
non-small cell lung carcinoma (5 papers, 2017 to 2023). A group of at least three distinct histological types of lung cancer, including non-small cell squamous cell carcinoma, adenocarcinoma, and large cell carcinoma. "For example, NUAK1 is highly expressed in non-small cell lung cancer (NSCLC) and knockdown of this gene served as a block in lung metastasis and invasive ability in a xenograft mouse model." (PMID 33750398, 2021).
osteosarcoma (5 papers, 2013 to 2020). A usually aggressive malignant bone-forming mesenchymal neoplasm, predominantly affecting adolescents and young adults. "In another study, both AMPK and the AMPK-related kinase NUAK1 (Ark5) were detected in a synthetic lethal RNA interference screen for kinases whose knock-down caused apoptosis of osteosarcoma (U2OS) cells over-expressing c-Myc." (PMID 23587167, 2013). "Consistent with this hypothesis, HTH-01-015 inhibition of NUAK1 in a PTEN-deficient osteosarcoma cell line has been shown to block the G1/S transition." (PMID 29566768, 2018). "Surprisingly, however, endogenous NUAK1 localized mainly to the nucleus of U2OS osteosarcoma cells; the staining occurred in a speckled pattern that partly co-localized with the nuclear pool of the protein phosphatase catalytic subunit beta (PPP1CB)." (PMID 32006464, 2020). "We employed mass spectrometry to identify proteins that specifically immunoprecipitated with stably overexpressed NUAK1 in osteosarcoma-derived U2OS cells (Fig-ure 1A)." (PMID 24785407, 2014).
cervical carcinoma (4 papers, 2019 to 2024). A carcinoma arising from either the exocervical squamous epithelium or the endocervical glandular epithelium. "Protein analysis confirmed that NUAK1 and NUAK2 were induced in a time-dependent manner in human fibroblasts, mammary cells (data shown for NUAK2 only), and HaCaT and human cervical carcinoma HeLa cells." (PMID 30622137, 2019).